CDK1 (cyclin dependent kinase 1)
Diseases named in the same sentence as CDK1 in open-access papers (continued):
Sharing a sentence is not in itself a finding about the gene and the disease.
cancer (continued). "The CDK1, CDK5, CDC20, CCNA2, CCNB1 and CCNB2 expression levels (tumor sample: n = 369 vs. normal sample: n = 160) were upregulated in HCC group compared with the non-carcinoma group (Analysis by GEPIA dataset)." (PMID 36605491, 2023). "Moreover, the GSCALite database was analyzed to evaluate the correlation between medicine sensitivity and CDK1, FAM111B and ZWINT according to the Cancer Therapeutics Response Portal (CTRP) and GDSC." (PMID 35406786, 2022). "In combination with the fact that ∆Np63α is a key transcription factor controlling cancer cell migration and metastasis in multiple SCC cancer types, our data indicate that CDK1 may facilitate metastasis of HNSCCs, by phosphorylating and inhibiting ∆Np63α." (PMID 35806389, 2022). "Further, the taxane-resistant DUTXR also showed enrichment of biomarkers that play significant roles in cancer progression, development, and maintenance of cancer stemness (CD44) and drug resistance (CDK1, CXCL8), indicating probable involvement of these genes in mCRPC development and progression." (PMID 36497496, 2022). "It should be noted that infinite proliferation potential is a common feature for most types of cancer, so CDK1, CCNB1, and KIAA0101 were broadly expressed and upregulated in a variety of cancers, making them unsuitable for use as CCA biomarkers but suitable for therapeutical targets." (PMID 36224755, 2022). "Although extensive evidence reveals a close relationship between CDK1 and cancer, there is no comprehensive pan-cancer analysis of CDK1 yet." (PMID 35681641, 2022). "In addition, CDK2 overexpression significantly attenuated the anti-cancer effect of erdafitinib by affecting the transcriptional activity and expression of E2F1, as well as the expression of CDK1." (PMID 36235266, 2022). "The expression of p21, CDK1 and cyclin B1 was shown to be altered in BAP31 knockdown cells, suggesting that regulation on cell cycle distribution contributed to BAP31 participated cancer cell migration." (PMID 35359416, 2022). "CDK1, CCNB1 and CDK2 are the key oncogenes that promote cell cycle progression in cancer cells." (PMID 35359459, 2022). "Importantly, our preclinical findings also illustrate how pharmacologic manipulation of key cell cycle regulators (CDK1 and/or CDK2) can potentially limit the efficacy of WEE1 inhibitors in cancer patients." (PMID 35315355, 2022). "Thus, this study aims to explore the role of CDK1-4, 6 expressions in HCC patients based on public cancer data." (PMID 35193513, 2022). "In pan-cancer levels, STIL showed consistent expression alteration with CDK1 and CCNB1." (PMID 35155425, 2022). "Therefore, v‐Src‐mediated CDK1 inactivation contributes to mitotic slippage in MTAs‐treated mitotically arrested cells, thus reducing MTA cytotoxicity and promoting cancer cell survival." (PMID 33465289, 2021). "In the end, the molecular function of Cdc20 in pan-cancer analysis indicated that BUB1, CCNA2, CCNB1, CDK1, MAD2L1, and PLK1 might play a critical role in its oncogenic function." (PMID 34527589, 2021). "In detail, they show that CDK1 interacts with the small ubiquitin-like modifier (SUMO)-specific enzyme and an ubiquitin-conjugating enzyme, which in turn intervenes with the SUMO-1-modified CDK6 and contributes to cancer development and progression." (PMID 33161487, 2021). "Moreover, CDK1 and CNNB1/2 have been identified as CIN signature genes whose overexpression correlates with CIN in cancer." (PMID 33168930, 2021). "Therefore, multiple strategies to overcome PARPi resistance have been designed to selectively disrupt HR in cancer cells, e.g., via combined inhibition of PARP and CDK1, and thus to re-sensitize the cells to PARPi." (PMID 34686201, 2021).
cancer (continued). "This suggests that overexpression of CDK1 on its own is sufficient to drive cell cycle progression of cancer cells, without the need for other CDKs to be overexpressed." (PMID 34503199, 2021). "Namely, FOXM1 promotes epithelial-mesenchymal transition and metastasis formation for breast and various other cancers, RRM2 contributes to poor survival and tamoxifen resistance development, while expression levels of CDK1, PLK1 and RACGAP1 were shown to be prognostic markers." (PMID 33852600, 2021). "Oncomine, TIMER and GEPIA web-based tools were used to evaluate and validate the mRNA expression of CDK-1 and CDK-4 in different cancer types (solid tumor and hematological malignancies), different CRC sections as well as clinico-pathological parameters of CRC in relation to normal tissues." (PMID 33732631, 2021). "In cancer cells with high levels of p‐TFCP2L1, CDK1, SALL4, and CD44 levels were significantly higher than in cells with low expression of p‐TFCP2L1, suggesting that a subset of p‐TFCP2L1‐positive cells could represent a population of bladder CSCs." (PMID 31709755, 2020). "In accordance with these recent data, we found in this study that genetic depletion of Fasn resulted in the lower growth rate of c-Myc/MCL1/Cre tumors as well as in the decrease of Cdk1, Cdk2, Skp2, and Survivin/Birc5 genes, which have been previously found to be regulated by FASN in cancer cells." (PMID 33187130, 2020). "In consonance with this observation, we found that patients whose tumors lacked anti-249T-P or anti-CDK1 staining had longer overall survival (OS; p = 0.048 and 0.036, respectively) than patients whose cancers showed with anti-249T-P staining." (PMID 32214089, 2020). "Compared to the noncancerous HDFs, higher levels of cyclin B1 and/or CDK1 were detected in a number of the cancer cell lines." (PMID 32575711, 2020). "Interestingly, the genes CDC20, CDCA8, MYBL2, C1QTNF6, CEP55, CDK1 and KIF14 were found to be more universal/common, since they mark multiple types of cancers not only in prognosis but also in diagnosis." (PMID 32489468, 2020). "In addition, both CDK1 upregulation and BRD4 hyperphosphorylation have been observed in BETi-resistant cancer cells." (PMID 32575711, 2020). "Furthermore, in MDR cancer cells, danazol reduced STAT3 phosphorylation as well as the expression of STAT3-regulated genes involved in cell survival, such as c-Myc, CDC25, and CDK1." (PMID 31406162, 2019). "In our research, up-regulation of p-ATM/p-CHK2, p-ATR/p-CHK1 and CycB/CDK1 by EBV-miR-BART8-3p in NPC may, at least partly, explain the high radioresistance of this deadly cancer." (PMID 31471531, 2019). "There is a signalling link between CDK1 and EZH2, with a relevant role in cancer cell invasion." (PMID 31591432, 2019). "The CDC25C protein is a phosphatase responsible for the dephosphorylation and activation of CDK1 to promote the transition of cells to mitosis, so NS1-inactivated CDC25C could inhibit cancer cell proliferation." (PMID 31487941, 2019). "In ER+ cancer cells, PIP5K1α acted on pSer-473 AKT, and was in complexes with VEGFR2, serving as co-factor of ER-alpha to regulate activities of target genes including cyclin D1 and CDK1." (PMID 30104711, 2019). "A prognostication scoring system based on the expression levels of RNASEH2A-, CDK1-, and CD151-related genes could effectively predict the survival rate of RCC cancer patients (with a mean difference of four years in ccRCC)." (PMID 29843367, 2018). "We noticed that, although identified independently, several of these aberration hubs were connected together through protein-protein interactions and formed a protein network that included several known cancer driver factors such as MYC, EGFR, PIK3C2B, CDK1, and KDR." (PMID 29861861, 2018). "BSA-GNPs in our study regulated CDK1 through up-regulation of Cdh1, so BSA-GNPs stabilizing microtubules may also lead to a potential cancer therapy." (PMID 30562921, 2018).
cancer (continued). "Of note, we found both CDK1 and CCNB1 in the list of switch genes shared by different cancer types." (PMID 28317894, 2017). "CDK1 was expressed in the cytoplasm of the cancer cells, but no expression was evident in normal tissues (Wilcoxon test, P < 0.001)." (PMID 28434945, 2017). "Taken together, our study indicates that KCTD12 exerts its effects in cancer by forming a complex with CDC25B and CDK1, and the phosphorylation of KCTD12 at serine 243 is necessary for the interaction of KCTD12 and CDK1, but it is not a crucial factor for the interaction with CDC25B." (PMID 28869606, 2017). "PP2A inhibition-induced sensitization to radiation and chemotherapy in cancer cells is believed to occur via several mechanisms, including sustained phosphorylation of Akt, MDM2, Plk1, TCTP and Cdk1, which are involved in apoptosis, cell cycle deregulation, and inhibition of DNA repair." (PMID 27527863, 2016). "It is likely that pCDC25C-Ser216 remained in the nucleus (without cytoplasmic sequestration) contributes to the cancer development by activating CDK1/cyclin B complex and leading to an un-thorough G2 arrest." (PMID 27801830, 2016). "In the tumor network, PVT1 competing for cancer related genes such as BRCA1, NOTCH2 and CDK1/4." (PMID 27580177, 2016). "The effects of 2-ME on Cdk1 expression and activity and on cyclin B1 expression have been widely investigated in numerous cancer cell lines, but not in HeLa cells." (PMID 26228523, 2015). "In initial clinical trials, maximal inhibition of Cdk1 did not appear to be very successful in the treatment of human cancers." (PMID 26423135, 2015). "Both CDK1 and CDK2 are potential cancer targets for which selective compounds are required." (PMID 25864384, 2015). "Also known as CYC202 or seliciclib, this purine analog primarily inhibits CDK2 and CDK5, as well as CDK1, CDK7 and CDK9 in several forms of human cancers." (PMID 25625291, 2015). "Possibly, Cdk1 inhibition works better as an anti-cancer strategy when the targeted cells do not arrest in G2 phase, but undergo a fatal mitosis." (PMID 26423135, 2015). "This study discovers an essential role of Cdk1-TAZ signalling in determining the tumor cell sensitivity to antitubulin drugs and suggests a novel signalling target for the treatment of antitubulin drug-resistant cancers." (PMID 26183396, 2015). "P276-00, a flavone with a specific CDK1/4/9 inhibition activity, has been studied for anticancer effects in several other cancers but not HNSCC." (PMID 23414419, 2013). "Vorinostat and Flavopiridol are anti-cancer agents involving the HDAC1, HDAC2 and CDK1 genes." (PMID 24564241, 2013). "From this transcriptional gene data, we show that overexpression of ANXA4 regulates genes that are known to be related to cancer, for example the activation of hyaluronan mediated motility receptor (RHAMM), AKT, and cyclin-dependent kinase 1 (CDK1) as well as the suppression of p21." (PMID 22970268, 2012). "One interesting finding is that PARP inhibitors selectively sensitise CDK1 compromised cancer cells, but not CDK1 compromised normal cells." (PMID 24970153, 2012). "Since CDC2 codes for CDK1, which is phosphorylated by WEE1, our results suggest a feedback loop that might be important for cancer." (PMID 21390271, 2011). "Cancer cell killing by PRGPRP, in a cyclic amphiphilic cassette, requires cells to be in cycle but does not perturb cell cycle distribution and is accompanied by altered relative Cdk4/Cdk1 expression and selective decrease in ATP levels." (PMID 21668989, 2011).
cancer (continued). "Proteomic expression levels of Cdk1 and Cdk4 are closely correlated in human cancers but not normal cells and have been shown to spontaneously go up and down together from experiment to experiment in several human cancer cell lines." (PMID 21668989, 2011). "Studies in other cancer cell lines measuring cell cycle effects of individual CDK2 depletion showed little change in cell cycle profiles of asynchronous cells due to compensation by other CDK family members, including CDK1 and CDK4/6." (PMID 20010939, 2010). "However, this CDK1 link is currently specific to HCC, and additional studies are needed to determine whether similar mechanisms operate across other cancer types." (PMID 41584036, 2026). "Even though CDK1 plays a critical role in cell cycle regulation, the clinical application of CDK1 inhibitors is hindered by their high toxicity and lack of efficacy in cancer patients." (PMID 41193441, 2025). "The binding of Alsterpaullone, Avotaciclib, Fostamatinib, Olomoucine, Seliciclib, and Naringin to CDK1 protein (PDB ID: 4Y72) at the TYR15 site was found to promote CDK1 phosphorylation, effectively halting the cell cycle at the G2-M phase and preventing unregulated cancer cell proliferation." (PMID 41009727, 2025). "However, studies on carcinogenesis by exogenous CDK1 in impaired wound healing have not been reported, and the therapeutic effect of CDK1 as a cancer treatment target varies depending on its phosphorylation regulatory site." (PMID 39865653, 2025). "Moreover, genes that are upregulated and downregulated at both RNA and protein levels across multiple types of cancers were identified and defined as PCUGs and PCDGs, respectively, which encompass a large number of oncogenes such as MKI67, TRIP13, SMC4, UBE2C, CDK1, and TOP2A." (PMID 39884577, 2025). "Furthermore, CDK1 and CDK2, critical regulators of the cell cycle, play a prominent role in cancer." (PMID 39457550, 2024). "Given that Cdk1 is a key kinase that activates the SAC and that inhibiting Wee1 extends mitosis in a SAC-dependent manner, it can be hypothesized that combining Wee1 and Kif18A inhibition may potentiate therapeutic effectiveness against aneuploid cancers." (PMID 39610707, 2024). "In addition, several studies have demonstrated that CDK1, through phosphorylation of BUB1, EZH2 and PPP1CA, alters cell cycle regulation, chromosome segregation, epigenetic control, and DNA replication, leading to cell dysfunction and diseases such as cancer." (PMID 38831458, 2024). "In addition, clinical trials performed on some cancer patients failed to respond to treatment because of low expression levels of CDK1." (PMID 37311884, 2023). "Besides the well-characterised modulators of CDK1, our analysis highlights a novel potential role for MYO3A, GSK3A and GRK6 kinases, whose expression profile is highly correlated with CDK1 itself and its modulators across cancer tissues." (PMID 37898722, 2023). "They activate cancer cell signaling pathways and transcription factors, including IGF1/α6β4 complex, FGFR2, TIMP, DNA replication and mTOR signaling, Smad7, KLF4, and TBX2, and downstream proto-oncogenes such as MYC, MET, and CDK1, which facilitate cancer progression." (PMID 37046676, 2023). "By analyzing the clinical significance and prognosis of G2/M related genes (PLK1, CDK1, CCNB1, and CCNB2) in various cancer tissues, we found that they were up-regulated in most cancer types, and their down-regulation showed better overall survival rates in cancer patients." (PMID 37007025, 2023). "There are no reports of pan-cancer analysis of CDK1 from an overall perspective." (PMID 36090896, 2022). "However, no pan-cancer analysis has been reported for CDK1, and the predictive role of CDK1 in immune checkpoint inhibitors (ICIs) therapy response remains unexplored." (PMID 36090896, 2022). "BUB1B and CDK1 may act in concert with HELLS, contributing to cancer malignancy and progression." (PMID 35774795, 2022).
cancer (continued). "However, after a long 72 h of exposure to RO-3306, 40% of the cancer cells were in an apoptotic state but only 10 percent of normal cells, suggesting some selectivity of CDK1." (PMID 34503199, 2021). "In the SW480 and SW1116 cancer cells, Western blot analyses showed that treatment by 100 nM CBG induced a significant, progressive decrease in the levels of cyclin B and conspicuous accumulation of CDK1-pT15, indicating activation of the G2/M cell cycle checkpoint." (PMID 34425836, 2021). "METTL3 knockdown could decrease CDK1 mRNAs with m6A modification, while VIRMA knockdown did not change the level of m6A modification in CDK1 mRNAs, indicating that m6A modification did not disturb the interaction between VIRMA and CDK1 in cancer cells." (PMID 33731118, 2021). "Therefore, CDK1 and CDK4 were found to be potential cancer therapeutic targets." (PMID 34290286, 2021). "Moreover, prior studies have demonstrated that inhibitors of BET, CDK1, HDAC, Protease, PI3K, and VEGFR could all decrease BRCA1 and other HRR factors at the protein level, thereby increasing the sensitivity of the cancer cell lines to PARP inhibition." (PMID 33589588, 2021). "We investigated the hypothesis that CDK1 and HSP90 signaling overlaps in the regulation of HIF1α, and combination treatment to target both CDK1 and HSP90 may lead to enhanced inhibitory effects towards HIF1α expression and function as well as improved anti-cancer efficacy." (PMID 34686682, 2021). "Moreover, the pan-cancer analysis of the molecular function of Cdc20 indicated that BUB1, CCNA2, CCNB1, CDK1, MAD2L1, and PLK1 might play a critical role in interaction with Cdc20." (PMID 34527589, 2021). "However, low selectivity and a lack of mechanism of action have led to the failure of CDK1 inhibitors, whereas BETi resistance emerged in certain cancers has dampened its efficacy." (PMID 32575711, 2020). "High levels of expression of CDK1 were correlated with high tumor grade (P < 0.001) and high tumor stage (P = 0.018), as well as with frequent LVI (P = 0.023), muscularis propria invasion (P = 0.011), distant metastasis (P = 0.016), and cancer‐specific death (P = 0.001)." (PMID 31709755, 2020). "α-Pinene, at 1000 μg/mL, inhibited the human carcinoma hepatocellular BEL-7402 cells proliferation, arresting cell growth in the G2/M phase of the cell cycle, decreasing gene and protein expressions of Cdc25C, and reducing the cycle dependence on kinase 1 (CDK1) activity." (PMID 32527068, 2020). "Understanding the role of CDK1 and PLK1 in the maintenance of centrosomes and primary cilia and in postmitotic differentiation programs is important not only for basic research but also for clinical practice because both these kinases are considered as attractive targets for cancer therapy." (PMID 31295970, 2019). "Furthermore, CDK1 and CDK2 are both drug targets of the investigational drug Alvocidib which is a synthetic flavonoid based on an extract from an Indian plant for the potential treatment of cancer." (PMID 29855504, 2018). "Moreover, the functions of CDK1/cyclin B1 in human cancer had not been properly elucidated similar to CDK4/CDK6/cyclin D. Multi-CDK inhibitors that target CDK1 are well-tolerated in cancer patients." (PMID 25914884, 2015). "However, CCNB1 is a regulatory subunit of CDK1 and is one of the main cyclin family members, it is not convenient to be directly manipulated in anti-cancer therapy." (PMID 27030811, 2015). "This study suggested that the PP2A/JNK/Sp1/CDK1 cell signaling pathway and autophagy/p21 pathway may be responsible for the G2/M cell cycle arrest and cytotoxicity by treatment with PP2A inhibitors in cancer cells." (PMID 26053095, 2015). "An extensive literature search has failed to provide an explanation for the relative elevation of Cdk1 in dying cancer cells following drug exposure and whether or not this might be related to necrotic cell death." (PMID 21668989, 2011).